RAE1 (ribonucleic acid export 1)
Diseases named in the same sentence as RAE1 in open-access papers (continued):
Sharing a sentence is not in itself a finding about the gene and the disease.
tumor (continued). "Previously, we used NKG2D to specifically deliver IL-2 to Rae-1 expressing TC-1 tumors in tumor-bearing mice." (PMID 24354786, 2013). "Histological analyses suggested that the GM-SCF, IL-21, and Rae-1 genes alone or in combination induced a cellular immune response against H22 tumor cells." (PMID 24350772, 2013). "Ectopic expression of RAE-1 in tumor cells also results in efficient clearance of tumor cells after subcutaneous transfer in vivo." (PMID 21966273, 2011). "From these studies we conclude that the interaction of the activating receptor NKG2D on NK cells with NKG2D ligands, such as Rae-1 expressed on PyVTu cells was essential for the NK cell-mediated killing of these virus-induced tumor cells." (PMID 20523894, 2010). "In addition, the combination of Nkg2d and Rae-1 mediated the activation of NK cells in the tumor model." (PMID 37585912, 2023). "The expression of Rae1 in tumor tissues was also upregulated when treated with cisplatin." (PMID 37253929, 2023). "Furthermore, the mRNA expression changes of Rae1 in tumor tissues and MB49 cells were consistent with those revealed by western blotting." (PMID 37253929, 2023). "Moreover, the multivariate Cox regression analysis showed that tumor status (HR = 2.042, P = 0.012) and RAE1 expression level (HR = 2.461, P = 0.002) were independent prognostic factors of OS in HCC patients." (PMID 35751040, 2022). "In addition to inhibitory receptors, NK cells also express stimulatory receptors such as natural killer group 2D (NKG2D) that bind to tumor antigens, RAE1 and H60, to mediate tumor rejection." (PMID 36248881, 2022). "Together, these results support that RAE1 accelerates tumor metastasis in vivo." (PMID 30814639, 2019). "Cytotoxic CD8+ T cells detect malignant-self either directly through interaction of the T-cell receptor (TCR) on CD8+ T cells with tumor antigens or indirectly in the form of so-called “danger signals” such as the retinoic acid early transcript-1 (RAE-1) and related ligands." (PMID 28220815, 2017). "According to their hypothesis, the high affinity NKG2DL Mult-1 released by the tumor cells blocks the engagement of NKG2D on NK cells and T cells by the NKG2DL Rae-1 on tumor-resident host cells and thereby prevents the NKG2D-induced anergy of NK cells." (PMID 29163533, 2017). "Tumor-infiltrating NK cells mice had elevated NKG2D in RAE-1-KO mice compared with WT controls." (PMID 29231815, 2017). "This could be explained by the lack of desensitizing RAE-1 expression on myeloid cells or the presence of sMULT1 in the serum of DEN-treated mice, preventing hypothetical desensitization via RAE-1-expressing tumours." (PMID 28128200, 2017). "Indeed, RAE-1-KO mice challenged with B16-MULT1 tumors exhibited superior tumor rejection compared with WT mice." (PMID 29231815, 2017). "This is due, at least in part, to an exaggerated atopic response to the tumor promoter 12-O-tetradecanoylphorbol-13-acetate (TPA), including upregulation of the keratinocyte stress-associated antigen Rae-1, which binds natural killer group 2D (NKG2D) on immune cells." (PMID 26763429, 2016). "This suggests that the 52A anti–Rae-1 mAb recognizes Rae-1–expressing cells and thus could be used to detect Rae-1 localization in tumor cells." (PMID 24495546, 2014). "Same as the neutrophils from naive mice, the tumor-promoting neutrophils could produce more IL-18, and express higher levels of NK-activating ligands RAE-1, MULT-1, and H60 after priming by IFN-γ and TNF-α." (PMID 25587026, 2014). "Recently, NKG2D ligand Rae-1 expression was also observed in tumor vasculature." (PMID 24565056, 2014). "However, thus far, little information has detailed the effects of GM-SCF and Rae-1 gene expression on Treg frequencies in a mouse tumor model." (PMID 24350772, 2013).
tumor (continued). "The expression of RAE-1 (and MULT1) is induced both constitutively and via the DNA damage response (DDR) pathway caused by the presence of cytosolic DNA during pathological cell conditions, with research focusing on various tumor cells, tumor vasculature, and viral infections." (PMID 39866909, 2024). "Interestingly, it has been reported that polyriboinosinic-polyribocytidilic acid (poly I:C)-treated macrophages increased NK cell-mediated cytotoxicity against tumor cells through increased surface expression of RAE-1 (an NKG2D ligand) as well as production of IL15." (PMID 37570749, 2023). "We evaluated whether tumor rejection was also impaired in the CD11c-Rae1 mice." (PMID 28815225, 2017). "Studies using CD11c-Rae1 mice with established transplantable solid tumors or in primary tumorigenesis models may provide valuable insight on the importance of NKG2D ligand expression by third-party cells on tumor surveillance and elimination." (PMID 28815225, 2017). "Consequently, immune cells easily identify tumor cells that highly express Rae-1." (PMID 24350772, 2013). "We showed that DTIC not only markedly upregulated Rae-1 and Mult-1 but also upregulated MHC-I expression on tumour cells, particularly in the form of DTIC/Ecapasome-2." (PMID 37945606, 2023). "PARADIGM pathway features corresponding to the mitotic genes TPX2, RAE1, UBE2C, AURKA show increased activity in tumours with high NCS, consistent with the known role of chromosome segregation errors in W-CIN." (PMID 35326573, 2022). "In tumor settings, engagement of NKG2D on NK cells led to NK cell activation and cytolysis of Rae-1-expressing myeloid cells." (PMID 29740438, 2018). "(F) WT or RAE-1-KO mice (n = 7–8) were challenged with 2 × 106 TRAMP-C2 cells s.c. and monitored for tumor growth." (PMID 29231815, 2017). "(E) WT or RAE-1-KO mice were challenged with 5 × 104 B16-MULT1 cells s.c. and monitored for tumor growth." (PMID 29231815, 2017). "Our observations indicate that the major tumor-protective mechanism identified in EPI-/- mice, namely signaling via Rae-1 and NKG2D, is attributable to the inherent structural defects in the epidermal barrier and not to the increase in the skin microbiota." (PMID 26763429, 2016). "In parallel, the expression of RAE-1 (P=0.0496), H60 (P=0.0316) and MULT-1 (P=0.0281) on the tumor cells from CpG ODN-treated mice were an average 1.5-fold increase, compared to those in PBS-treated mice." (PMID 27448968, 2016). "Overexpression of mouse and human NKG2D ligands such as Rae-1, H60, MULT-1, and MICA on tumor cells resulted in a retarded tumor growth or tumor rejection due to NK-cell mediated cytolysis." (PMID 23776472, 2013). "To determine both the functionality of the Gaussia luciferase and the binding specificity of the NKG2D-Fc-GLuc protein to Rae-1-expressing tumor cells, we incubated NKG2D-Fc-Gluc with Rae-1-expressing TC-1 tumor cells." (PMID 22509395, 2012). "A nomogram was constructed to predict the survival probability at 1-, 3-, and 5-year by integrating RAE1 expression level and clinicopathological characteristics (N stage, gender (male or female), age, prothrombin time (PT), AFP level, tumor status, and pathologic stage)." (PMID 35751040, 2022). "Furthermore, in order to confirm the positive correlation between RAE1 and ZEB1 in an in vivo system, IHC was performed with anti-ZEB1 antibody in tumor tissues retrieved from the xenograft experiment." (PMID 30814639, 2019). "Under selective pressure, tumor cell with high expression of targeting expression (RAE1) were destroyed while RAE1low/negative tumor cells survived." (PMID 30935414, 2019). "RAE-1 was highly expressed on tumors developing in both wild-type and Klrk1−/− mice indicating that tumor progression was not the consequence of escape via ligand editing." (PMID 30150983, 2018).
tumor (continued). "In parallel, compared with those from PBS-treated mice, the expression of MULT-1 (P=0.0241) on the tumor cells from CpG ODN-treated mice were 2-fold increase, while no obvious change in the expression of RAE-1 and H60 on the tumor cells." (PMID 27448968, 2016). "Rae1 expression is low or absent in normal tissues and it is constitutively expressed on some tumor cells." (PMID 26146488, 2015). "The anti–Rae-1 antibody showed positive staining on CT26–Rae-1 tumor sections but not control CT26-GFP tumor sections." (PMID 24495546, 2014). "We further demonstrated that NKG2D-Fc bound to Rae-1-expressing tumor cells through the NKG2D component, rather than the Fc component, since Con-Fc (which does not have the NKG2D component) failed to generate significant binding." (PMID 22509395, 2012). "NKG2D-Fc bound to all three of the NKG2D ligand-expressing tumor cell lines, but not to the Rae-1-negative tumor cells." (PMID 22509395, 2012). "Rae-1 is a ligand which activates NK cells (NK1.1+CD3-) via the NKG2D receptor, however sustained elevation of Rae1 results in impaired NK cell function and a subsequent decrease in anti-tumour immunosurveillance." (PMID 21291541, 2011). "Treg are believed to inhibit NKG2D-mediated NK cell killing, and in accordance with this observation, both tumour cell lines (B16F10 and B16FasL) used in these experiments express the NK2GD ligand Rae-1, in contrast to other studies in which NKG2D ligands were transfected into tumour cells." (PMID 17294404, 2007). "Similarly, BubR1-insufficient and Bub3/Rae1-haploinsufficient mice do neither show increased spontaneous tumor formation." (PMID 39466849, 2024). "Similarly, in the case of lymphokine-activated NK cells or NK cells generated by the enforced expression of NK receptor ligands, such as Rae1/H60/Mult-1 (NKG2D-L), the effector cells eliminate only MHC-negative tumor cells, resulting in the relapse by MHC-positive tumor cells." (PMID 28993781, 2017). "In line with our hypothesis proposing that NKG2D ligand expression is maintained rather than immunoedited in this type of tumour, we observed that RAE-1 was similarly expressed in both Klrk1+/+ and Klrk1−/− mice." (PMID 28128200, 2017). "Accordingly, repression of RAE1, a mitotic checkpoint regulator, as well as CDKN2A, a tumor suppressor that inhibits G1/S transition and establishes cell cycle arrest, could further support the hypothesis of enhanced proliferative potential of NEXBTL100 extract." (PMID 27827897, 2016). "In contrast, haploinsufficiency of Bub3 or Rae1 did not result in increased tumorigenesis, and some mouse models even showed decreased tumor formation when challenged with carcinogens, suggesting that the relationship between impaired SAC signaling, aneuploidy and tumor onset is complex." (PMID 26015801, 2015). "Conversely, the tumor-promotional neutrophils recovered the expression of Rab27a and Trail, resumed the activation levels of PI3K and p38 MAPK pathways in response to stimuli, and expressed higher levels of IL-18 and NK-activating ligands such as RAE-1, MULT-1, and H60." (PMID 25587026, 2014). "To determine if the purified NKG2D-Fc could bind to murine NKG2D ligand-expressing tumor cells, we selected three NKG2D ligand-expressing tumor cell lines (TC-1, MOSEC, and OVHM; all express Rae-1, a murine NKG2D ligand) and one Rae-1-negative tumor cell line (B16F10)." (PMID 22509395, 2012). "Also, animal studies revealed that the secreted form of MULT1, the mouse equivalent of ULBP-1 with a unique high affinity, does not downregulate NKG2D but rather favors tumor rejection by stabilizing NKG2D expression and preventing NK cell desensitization induced by RAE-1 on myeloid cells." (PMID 30150983, 2018).
cancer (32 papers, 2011 to 2024). A tumor composed of atypical neoplastic, often pleomorphic cells that invade other tissues. "To investigate the molecular mechanisms underlying the role of RAE1 in mediating cancer metastasis, we performed gain of function studies using in vitro models." (PMID 30814639, 2019). "We showed that Rae1 over-expression could promote proliferation of human cancer cells in culture, and our data suggests that Rae1 protein may accumulate upon loss of Hippo signaling in cancer cells." (PMID 27494403, 2016). "The RAE1 gene specifically has been shown to induce aggressive cancer phenotypes by mediating EMT via ZEB1 expression." (PMID 36835368, 2023). "In the present study, we analyzed RAE1 expression profile in different types of human cancer using the TIMER database." (PMID 35751040, 2022). "In an opposite way, knockdown of RAE1 in mesenchymal-like MDA-MB-231 cells reduced cancer cell invasion and migration." (PMID 30814639, 2019). "Collectively, these results suggest RAE1 positively regulates ZEB1 expression during cancer progression." (PMID 30814639, 2019). "In conclusion, our results, which demonstrate the functional role of RAE1 in cancer cell migration and invasion via EMT involvement, imply an important role for RAE1 during specific stages of cancer progression and metastasis." (PMID 28181567, 2017). "Cancer cells that express Rae-1 are readily identified by immune cells that facilitate their removal, based on the expression of the Rae-1 protein." (PMID 28938619, 2017). "Together, this indicates a potential impact of the BUB3/RAE1-complex on longevity and cancer resistance in both mole rat species." (PMID 29084988, 2017). "Given the role of RAE1 in mRNA transport and spindle assembly, alterations in its expression or function may contribute to the genomic instability observed in cancer cells." (PMID 39080077, 2024). "In cancer, RAE1, which is driven by super-enhancers, exhibits high protein levels." (PMID 38577683, 2024). "However, other studies have shown that RAE1 promotes cancer progression by regulating peroxisome proliferator-activated receptor alpha (PPARα)-mediated lipid metabolism and regulating EMT signals." (PMID 39080077, 2024). "The overexpression and dysregulation of RAE1 could lead to chromosome missegregation, instability and multipolar spindles, contributing to cancer development and progression." (PMID 35751040, 2022). "Indeed, candidate genes involved in maintaining genome stability, such as RAE1, SETD2, and CLTCL1, are attractive candidates for broad cancer susceptibility." (PMID 34067022, 2021). "This increased expression of RAE1 was observed on both cancer cells and CD45+ immune cells." (PMID 29399400, 2018). "Accordingly, it is important to note that RAE1 might contribute to oncogenesis and cancer progression." (PMID 28181567, 2017). "Our CD11c-Rae1 mouse can be used as a model to mimic this phenomenon that occurs in cancer patients to design therapies that may restore NKG2D expression and function in vivo." (PMID 28815225, 2017). "To determine the level of Rae-1 expression on the murine cancer cell lines CT26, B16F10, LLC, TC1, and K7M3, we incubated cells with the 52A anti–Rae-1 mAb and then fluorescein isothiocyanate (FITC)-conjugated goat anti-mouse IgG and performed flow cytometry." (PMID 24495546, 2014). "We found significant enrichment of RAE1, a SE60 cis direct target, and EPHA2, a SE14 cis direct target, within the cancer cell fraction as compared to the normal cell fraction (Wilcoxon Rank Sum tests, Bonferroni-corrected p-values < 2.2e−308 and average logFC ≥ 0.1)." (PMID 35869079, 2022). "The Raet1 gene family (not to be confused with ribonucleic acid export 1, Rae1) was originally identified by its expression in a mouse carcinoma cell line in response to retinoic acid treatment." (PMID 32153361, 2020).
cancer (continued). "Expression of Rae-1 is combined with NKG2D and mediated by the DAP10 pathway (the “self-induction hypothesis”), making cancer cell expression of Rae-1 easily identified by immune cells and hence removal of cancer cells that express it." (PMID 24350772, 2013). "In addition, we found that cis direct target genes annotated for each SE (such as RAE1 and EPHA2) were more highly expressed in the cancer cells compared to the stromal/non-malignant cells within HGSOC tumors." (PMID 35869079, 2022).
infection (16 papers, 2010 to 2025). The state of being infected such as from the introduction of a foreign agent such as serum, vaccine, antigenic substance or organism. "Crucially, NS1 expression also reduces RAE1•NUP98 complex levels during infection, a biologically significant effect, as RAE1+/− or NUP98+/− cells show increased sensitivity to IAV infection." (PMID 41101500, 2025). "Previously, we showed that MCMV gene expression was necessary to induce RAE-1 expression during infection." (PMID 27874833, 2016). "If class IA PI3K activation alone is sufficient to induce RAE-1 induction, it should occur in response to many cellular stimuli independently of infection." (PMID 21966273, 2011). "Altogether, our results suggest that expression of viral genes at an early stage upon infection prior to viral replication is necessary for the induction of RAE-1." (PMID 21966273, 2011). "Using this virus, we observed RAE-1 surface expression starting 18 hours post-infection with an even higher expression at 24 hours post-infection." (PMID 21966273, 2011). "UV inactivation significantly impaired the ability of MCMVΔ152 to induce expression of RAE-1 both at the RNA and protein levels throughout the course of the infection." (PMID 21966273, 2011). "Thus, we tested if depletion of either Rae1 or Nup98 altered hSpt16SUMO levels in mock-infected cells or inhibited hSpt16SUMO depletion during VSV-eGFP infection." (PMID 40060670, 2025). "Notably, 9 nucleoporins (NUP58, NUP214, NUP98, NUP54, NUP62, NUP88, NUP153, POM121/NUP121 and RANBP2/NUP358) and the mRNA export factor Rae1 were present in both the CebN infection and transfection interactomes." (PMID 38712050, 2024). "Here, we illustrated that UV-inactivated viral particles were sufficient to stimulate the IFN response, but expression of RAE-1 proteins was absolutely dependent on active infection and manipulation of the host cell machinery; activation of PI3K signaling being one example of such manipulation." (PMID 21966273, 2011). "It recognizes ligands upregulated by transformation, infection or cell stress, such as MICA/MICB and ULBP family members in humans, and Rae1, H60, and MULT1 in mice." (PMID 32415229, 2020). "Co-staining experiments demonstrated that RAE-1 induction occurs only in infected cells, suggesting that RAE-1 induction is a direct consequence of infection." (PMID 21966273, 2011). "Upon infection of fibroblasts with MCMV for 24 hours, there was a significant induction of RAE-1 expression at the RNA level." (PMID 21966273, 2011). "MX2 also modestly enhanced HIV-1WT infection upon NUP62, RAE1, and TNPO1 knockdown." (PMID 39853118, 2025). "Our new data showing that CebN binds NUPs and Rae1 and perturbs nuclear translocation of STAT1 may be the missing link needed to understand how C.t. establishes a persistent infection in spite of robust IFN-γ production." (PMID 38712050, 2024). "In our studies, we did not see differences in Rae-1 (distantly related to MHC class I proteins) expression in CD55 KO mice following infection with B. crocidurae." (PMID 36036625, 2022). "Infection of fibroblasts with MCMVΔ152 for 24 hours in the presence of PAA did not inhibit RAE-1 induction, indicating that viral DNA replication and late gene expression are dispensable for RAE-1 induction." (PMID 21966273, 2011). "The phenomenon of NK cell recognition and response to induced-self molecules has previously been implicated in both infections and oncogenesis, where ligands MULT1, H60, and Rae-1) for the activating receptor NKG2D are preferentially induced upon infection or cellular transformation." (PMID 21829360, 2011). "Moreover, in SCID mice on day 6 post infection, when spleens have a high PyV load, macrophages and DC, cell types known to be infected with PyV, did not up-regulate Rae-1 expression (data not shown)." (PMID 20523894, 2010).